MIR3681HG (MIR3681 host gene)
Gene: Long non-coding RNA gene on chromosome 2 (11,829,690 to 12,702,919, forward strand). Ensembl gene ENSG00000224184.
Diseases named in the same sentence as MIR3681HG in open-access papers:
MIR3681HG is named in the same sentence as 1 disease in open-access papers, as found by Europe PMC text mining. Sharing a sentence is not in itself a finding about the gene and the disease.
MIR3681HG shares sentences with these, for which no sentence is quoted: cancer (1 paper).